PCBP2 (poly(rC) binding protein 2)
Description:
Single-stranded nucleic acid binding protein that binds preferentially to oligo dC. Major cellular poly(rC)-binding protein. Also binds poly(rU). Acts as a negative regulator of antiviral signaling. Negatively regulates cellular antiviral responses mediated by MAVS signaling. It acts as an adapter between MAVS and the E3 ubiquitin ligase ITCH, therefore triggering MAVS ubiquitination and degradation. Negativeley regulates the cGAS-STING pathway via interaction with CGAS, preventing the formation of liquid-like droplets in which CGAS is activated. Together with PCBP1, required for erythropoiesis, possibly by regulating mRNA splicing (By similarity). (Microbial infection) In case of infection by poliovirus, binds to the viral internal ribosome entry site (IRES) and stimulates the IRES-mediated translation. Also plays a role in initiation of viral RNA replication in concert with the viral protein 3CD.
Synonyms: HNRPE2; hnRNP-E2; HNRNPE2
Tractability: Small molecule: a structure with a bound ligand is known; it has a binding pocket of medium quality. PROTAC: UniProt records ubiquitination sites on it; ubiquitination databases record sites on it; its protein half-life has been measured.
Gene: Protein-coding gene on chromosome 12 (53,451,900 to 53,481,162, forward strand). Ensembl gene ENSG00000197111.
Subcellular location: Nucleus; Cytoplasm
Subcellular location (Human Protein Atlas): Cytosol; Nucleoplasm
Pathways (Reactome):
Metabolism of RNA: Processing of Capped Intron-Containing Pre-mRNA; mRNA Polyadenylation; mRNA Splicing - Major Pathway
Disease: Dengue Virus-Host Interactions; SARS-CoV-1 activates/modulates innate immune responses
Immune System: Negative regulators of DDX58/IFIH1 signaling
Gene Ontology:
Molecular function: enzyme binding; lncRNA binding; promoter-enhancer loop anchoring activity; protein binding; RNA binding; ubiquitin protein ligase binding; single-stranded DNA binding; DNA binding; nucleic acid binding
Biological process: chromatin looping; IRES-dependent viral translational initiation; negative regulation of cGAS/STING signaling pathway; negative regulation of defense response to virus; proteasome-mediated ubiquitin-dependent protein catabolic process; viral RNA genome replication; mRNA metabolic process; positive regulation of transcription by RNA polymerase II
Cellular component: cytoplasm; cytosol; extracellular exosome; focal adhesion; membrane; nucleoplasm; nucleus
Genetic constraint (gnomAD): Loss-of-function variants: 1 observed, 34.01 expected, observed/expected ratio (o/e) 0.0294, 90% interval 0.009 to 0.14. The upper end of that interval is the gene's LOEUF score, 0.14, which puts it in group 1 of 6, group 1 being the genes least tolerant of losing a copy. Missense variants: 137 observed, 388.72 expected, observed/expected ratio (o/e) 0.35, 90% interval 0.31 to 0.41. Synonymous variants: 151 observed, 144.05 expected, observed/expected ratio (o/e) 1.05, 90% interval 0.92 to 1.2.
Homologues: Orthologues: chimpanzee PCBP2 (100% identical), guinea pig PCBP2 (100% identical), macaque PCBP2 (98% identical), mouse Pcbp2 (98% identical), pig PCBP2 (98% identical), tropical clawed frog pcbp3 (86% identical), rat AC128212.1 (85% identical), zebrafish pcbp2 (78% identical), Drosophila melanogaster mub (51% identical), Caenorhabditis elegans pes-4 (36% identical), Drosophila melanogaster ps (23% identical), Drosophila melanogaster Imp (20% identical), and 4 more. Paralogues in human: PCBP1 (83% identical), PCBP3 (73% identical), PCBP4 (52% identical), HNRNPK (35% identical), IGF2BP2 (30% identical), KHSRP (28% identical), FUBP1 (28% identical), FUBP3 (27% identical), IGF2BP1 (27% identical), IGF2BP3 (26% identical), NOVA2 (24% identical), NOVA1 (23% identical).
Diseases named in the same sentence as PCBP2 in open-access papers:
PCBP2 is named in the same sentence as 63 diseases in open-access papers, as found by Europe PMC text mining. Sharing a sentence is not in itself a finding about the gene and the disease. The quoted sentences say what the papers report.
viral infection (16 papers, 2010 to 2026). "The association between PCBP2 and cGAS was detected under both normal physiological and viral infection conditions." (PMID 35322803, 2022). "Collectively, these findings suggest that PCBP2 and cGAS form a complex in cells and the association of two proteins is likely modulated by viral infection." (PMID 35322803, 2022). "To further explore the mechanism underlying the regulation of cGAS in the context of viral infection, we performed co-immunoprecipitation (Co-IP) experiments in combination with mass spectrometry assays and identified PCBP2 as a cGAS-interacting protein." (PMID 35322803, 2022). "During virus infection, PCBP2 can associate with MAVS that acts as a scaffold to enhance AIP4-mediated degradation of MAVS17." (PMID 26348439, 2015). "IRTKS recruits the E2 ligase Ubc9 to sumoylate PCBP2 in the nucleus, which causes its cytoplasmic translocation during viral infection." (PMID 26348439, 2015). "Given that PCBP2 associates with cGAS and that this association is regulated by viral infection, we reasoned that PCBP2 might regulate cGAS-STING-mediated antiviral signaling by targeting cGAS." (PMID 35322803, 2022). "However, the underlying mechanism by which PCBP2 undergoes nuclear export during virus infection is still unknown." (PMID 26348439, 2015). "However, it is unknown how PCBP2 relocalizes to the cytosol where it associates with MAVS on virus infection." (PMID 26348439, 2015). "How PCBP2 translocates to the cytosol following virus infection is an interesting question that requires further investigation." (PMID 35322803, 2022). "The difference is that PCBP1 is stably expressed both in viral and resting states, while the basic expression of PCBP2 overlaps, but it is rapidly induced after the virus infection." (PMID 34566944, 2021). "For example, K48-linked ubiquitination of MAVS mediated by the E3 ubiquitin ligase AIP4 (also known as Itch) is promoted by the poly (C)-binding protein 2 (PCBP2), which is upregulated after viral infection." (PMID 32536927, 2020). "Endogenous PCBP2 primarily resides in the nucleus but relocalizes to the cytoplasm where it initiates MAVS degradation on viral infection." (PMID 26348439, 2015). "Therefore, excessive expression or knockdown of PCBP2 would suppress or promote the cellular inflammatory response to viral infection, respectively." (PMID 29327729, 2018). "Thus, we speculate that differences in the structures of the IRESs of picornaviruses may lead to different roles of PCBP2 in viral infection." (PMID 39300570, 2024). "Finally, after its induced synthesis following viral infection, poly(RC) binding protein 2 (PCBP2) negatively regulates the RIG-I/MAVS signaling pathway by interacting with MAVS and recruiting E3 ligase atrophin-1-interacting protein 4 (AIP4) for MAVS degradation by the proteasome." (PMID 29642643, 2018). "Then we examined whether PCBP2 or IRTKS underwent sumoylation during virus infection." (PMID 26348439, 2015). "Finally, there are reports that PCBP2 expression is stimulated during viral infection." (PMID 22438951, 2012). "Overexpression of JAK1, TYK2, MAP2K1, IFNG, TRPM2, and ADCY9 significantly inhibited viral infection, whereas overexpression of SNX27, GATA4, EHMT2, PCBP2, SMARCA4, and SLX4 enhanced viral infection." (PMID 40530850, 2025). "During viral infection, IRTKS can recruit ubiquitin-conjugating enzyme 9 (Ubc9) to SUMOylate PCBP2 within the cell nucleus, leading to cytoplasmic translocation of PCBP2 and then triggering degradation of the mitochondrial adapter MAVS to downregulate the RIG-I antiviral response." (PMID 39192031, 2024). "Upon viral infection, EPRS may protect the mitochondrial antiviral signaling protein (MAVS) by blocking PCBP2-mediated ubiquitination." (PMID 36034844, 2022).
viral infection (continued). "During viral infection, NLRX1 was also demonstrated to negatively regulate RIG-I activation through interaction with poly(rC) binding protein 2 (PCBP2) and mitochondrial anti-viral signaling (MAVS) via its NACHT domain to cause lysine 48 (K48)-linked polyubiquitination and degradation of MAVS." (PMID 32012730, 2020). "Notably, as both UNR and PCBP2 can interact with PABP, we can propose that these additional interactions may be important, at least at the initial stages of viral infection, before the synthesis of viral proteins (including 2A protease) has been accomplished." (PMID 36555135, 2022). "However, during virus infection, MAVS is proteolysed by a proteasome-dependent PCBP2/AIP4 axis." (PMID 20532218, 2010). "In addition, sumoylated PCBP2 neither affect the interaction between MAVS and PCBP2, nor the association of RIG-I or MDA5.These data indicate that the sumoylated PCBP2 leads to its nuclear export during the progress of virus infection." (PMID 26348439, 2015).
breast carcinoma (14 papers, 2017 to 2025). "Recently, lnc030 has been shown to promote cholesterol synthesis in breast cancer stem cells (BCSCs) by cooperating with poly(rC) binding protein 2 (PCBP2) to stabilize SQLE mRNA, which leads to increased cholesterol production." (PMID 37939296, 2024). "Top-ranked Stem.Sig genes, such as EMC3, BECN1, VPS35, and PCBP2, showed improved immune response after knockout in melanoma, renal carcinoma, breast carcinoma, and colon adenocarcinoma from multiple CRISPR datasets." (PMID 35488273, 2022). "Functionally, PCBP2 promoted the carcinogenesis and metastasis of breast cancer by directly regulating the expression of ubiquitin recognition factor in ER-associated degradation 1 (UFD1) and 5’-nucleotidase ecto (NT5E) via binding to their 3’UTRs." (PMID 36059653, 2022). "A recent study showed that the expression of PCBP2 protein was increased significantly in breast cancer tissues and cell lines, which was due to selective cleavage and polyadenylation (APA)." (PMID 36059653, 2022). "Overexpression of PCBP2 promotes the proliferation and metastasis of breast cancer cells by maintaining the mRNA stability of UFD1 and NT5E." (PMID 36052258, 2022). "In breast cancer, RNA sequencing analysis revealed that PCBP2 regulates the expression of NT5E by directly binding the 3′UTR (untranslated region) and enhancing the oncogenic activity of human breast cancer cells." (PMID 33430239, 2021). "A recent study of breast cancer highlighted the regulatory role of RNA binding by PCBP3 (paralog of PCBP1 along with PCBP2) on mRNA stability and induction of epithelial-mesenchymal transition (EMT)." (PMID 29335020, 2018). "In addition, in breast cancer stem cells (BCSCs), lnc030 maintains self-renewal capacity and tumorigenicity by cooperating with poly(rC) binding protein 2 (PCBP2) to stabilize SQLE mRNA, increasing cholesterol synthesis." (PMID 40722703, 2025). "Moreover, the oncogenic role of PCBP2 has been verified in various malignancies including glioblastoma and breast cancer." (PMID 39366930, 2024). "Recently, the RNA binding protein poly(C) binding protein 2 (PCBP2), which is a member of a class of PCPB post-transcriptional regulatory molecules that can bind RNA and proteins, was shown to be upregulated in human breast cancer and associates with poor survival." (PMID 33430239, 2021). "PCBP2 binds to the 3’UTR of UFD1 and NT5E to upregulate the expression of these two downstream genes, which ultimately promotes the development of breast cancer." (PMID 36052258, 2022). "We found that hypoxia induced exon 11 skipping of PCBP2-202 (ENST00000447282) in MCF7 cells, and this was also reproducible in the highly metastatic triple negative MDA-MB-231 breast cancer cells." (PMID 28642487, 2017). "In breast cancer, lnc030 cooperated with poly(rC) binding protein 2 to stabilize SQLE mRNA, resulting in an increase in cholesterol synthesis, which in turn activated PI3K/Akt signaling, which is involved in the self-renewal of breast cancer stem cells to keep their stemness." (PMID 38612682, 2024).
glioma (13 papers, 2016 to 2025). A benign or malignant brain and spinal cord tumor that arises from glial cells (astrocytes, oligodendrocytes, ependymal cells). "While PCBP2 is upregulated in glioma tissues and cell lines, the development and proliferation of glioma are suppressed when it is knocked down or when its inhibitor microRNA-214 is applied." (PMID 36358495, 2022). "SIRT6 is downregulated in human glioma tissues and deacetylates H3K9ac on the promoter of PCBP2 to downregulate PCBP2 expression and inhibit glioma cell growth." (PMID 35463332, 2022). "The results indicated that knockdown of PCBP2 inhibited glioma cell migration and invasion in vitro." (PMID 26761212, 2016). "Knockdown of PCBP2 inhibits glioma growth in vitro and in vivo through inhibiting cell cycle progression and inducing apoptosis." (PMID 26761212, 2016). "After transfection with NC siRNA and PCBP2 siRNA for 48 hours in the same 4 glioma cell lines, transwell migration assays, matrix invasion assays and wound-healing assays were performed." (PMID 26761212, 2016). "In our previous work, we have demonstrated that ARHGDIA is a target mRNA of the RNA-binding protein PCBP2 in gliomas, on the basis of RIP-Chip data and biotin pull-down assays." (PMID 26761212, 2016). "Our previous study has shown that the RNA-binding protein PCBP2 is increased in human glioma tissues and cell lines." (PMID 26761212, 2016). "Consistently with the results of the overexpression of ARHGDIA, knockdown of PCBP2 also reversed the mesenchymal-like characteristics of glioma cells." (PMID 26761212, 2016). "The rescue study suggested that PCBP2 influences glioma migration and invasion directly through ARHGDIA." (PMID 26761212, 2016). "We sought to elucidate the interaction between PCBP2 and miR-151-5p/miR-16 in promoting the motility and invasiveness of glioma cells through downregulating ARHGDIA." (PMID 26761212, 2016). "Moreover, previously, we revealed that PCBP2 is overexpressed in gliomas, and clinical studies also demonstrated that GBMs with a high expression of PCBP2 have a poor prognosis." (PMID 32272554, 2020). "PCBP2 was also reported to promote glioma cell growth both in vitro and in nude mice." (PMID 29744291, 2018). "PCBP2 may facilitate miR-151-5p and miR-16 promotion of glioma cell migration and invasion through mitigating the function of ARHGDIA." (PMID 26761212, 2016). "However, the knockdown of PCBP2 inhibited glioma growth both in vitro and in vivo by suppressing cell‐cycle and the apoptosis mediated by caspase‐3, showing that PCBP2 may act as a promoter of glioma development." (PMID 34482648, 2021). "Next, we investigated whether PCBP2 affects the glioma migration and invasion via ARHGDIA." (PMID 26761212, 2016). "The regulatory actions of PCBP2 on critical signaling pathways, including TGF-β/Smad, are of particular interest owing to their potential impact on the growth of gliomas." (PMID 40051782, 2025). "For example, YTHDF2 promotes glioma malignancy by degrading UBXN1 mRNA, while METTL3-mediated m6A modification enhances glioma metastasis by stabilizing PCBP2." (PMID 38171932, 2023). "The experimental study demonstrated that PCBP2 could activate TGF-beta pathway, thus promoting the development and progression of glioma." (PMID 34631793, 2021).
bladder cancer (8 papers, 2019 to 2025). "Human bladder cancer cell lines (T24 and 5637) with PCBP2 stably knocked down were constructed and validated." (PMID 37810965, 2023). "In addition, a direct relationship between the increase in KCNQ10T1 and the proliferation and migration of bladder carcinoma cells was observed through the modulation of mir-145-5p/PCBP2." (PMID 34209776, 2021). "PCBP2 stabilizes the mRNA of the ferroptosis inhibitor SLC7A11, which inhibits ferroptosis in tumors and accelerates bladder cancer progression." (PMID 39816681, 2025). "Phosphoglycerol dehydrogenase, by binding and regulating PCBP2 [Poly(rC) binding protein 2] protein expression to promote the mRNA stability of SLC7A11 (the catalytic subunit of system Xc–), can inhibit cell ferroptosis and ultimately promote the malignant progression of bladder cancer." (PMID 36578828, 2022).
gastric cancer (7 papers, 2018 to 2025). A primary or metastatic malignant neoplasm involving the stomach. "A high expression level of PCBP2 was associated with a more malignant nature of gastric cancer cells and a worse outcome for patients with gastric cancer." (PMID 29744291, 2018). "Therefore, a high level of PCBP2 was associated with a poor prognosis in patients with gastric cancer." (PMID 29744291, 2018). "PCBP2 associated with CDK2 could be used as a potential biomarker for gastric cancer therapy." (PMID 29744291, 2018). "Functional depletion of PCBP2 suppressed cell viability and decreased the percentage of cell mitosis in human gastric cancer cells." (PMID 29744291, 2018). "In the present study, we systematically examined the promoting role of PCBP2 in human gastric cancer cells." (PMID 29744291, 2018). "Small hairpin RNA‐mediated depletion of PCBP2 dramatically decreased the viability of gastric cancer cells." (PMID 29744291, 2018). "A high level of PCBP2 was correlated with worse postoperative relapse‐free survival and overall survival rates of gastric cancer patients." (PMID 29744291, 2018). "Based on the results in clinical tissues, PCBP2 was inferred to be an oncogene in human gastric cancer." (PMID 29744291, 2018). "In the present study, we demonstrated that the expression level of PCBP2 was higher in human gastric cancer tissues compared to adjacent normal gastric tissues." (PMID 29744291, 2018). "LINC02535 was found to be upregulated in poorly differentiated gastric cancer and cervical cancer, where it was shown to directly interact with poly-binding protein 2 (PCBP2) in the cytoplasm, regulating cell proliferation, DNA damage repair, and tumor progression." (PMID 40699747, 2025). "Moreover, Poly (rC) binding protein 2 (PCBP2), acting as an oncogene in gastric cancer cells, promotes the CDK2 activity by direct interaction and is overexpressed in gastric cancer, where the higher expression is associated with poor survival of the patients." (PMID 36769170, 2023). "Higher levels of PCBP2 are connected with worse prognosis in glioblastoma and gastric cancer." (PMID 34335745, 2021). "In the present study, we examined the expression of PCBP2, which was much higher in human gastric cancer tissues compared to adjacent normal gastric tissues, and found that the over‐expression of PCBP2 is correlated with poor survival among gastric cancer patients." (PMID 29744291, 2018). "Moreover, we determined that CDK2 mediated the promoting role of PCBP2 in human gastric cancer cells." (PMID 29744291, 2018). "Hence, the promoting role of PCBP2 in the viability of human gastric cancer cells was mediated by CDK2." (PMID 29744291, 2018). "In summary, the present study examined the oncogenic role of PCBP2 in human gastric cancer cells." (PMID 29744291, 2018). "As a result, PCBP2 dramatically promoted the viability of human gastric cancer cells." (PMID 29744291, 2018). "Poly(rC) binding protein 2 (PCBP2) is an RNA‐binding protein that contributes to mRNA stabilization, translational silencing and enhancement and it has been implicated as a promoter of gastric cancer growth." (PMID 29744291, 2018). "Therefore, PCBP2 facilitated the viability of gastric cancer cells specifically by regulating CDK2." (PMID 29744291, 2018). "CDK2 might mediate the tumor‐promoting role of PCBP2 in human gastric cancer cells." (PMID 29744291, 2018). "On the contrary, in gastric cancer, PCBP2 interacts with the 3′UTR region of CDK2 transcript, thereby accelerating the cell cycle of gastric cancer cells and promoting tumorigenesis." (PMID 39366930, 2024). "CDK2 partly mediated the promoting role of PCBP2 in human gastric cancer cells and the expression levels of PCBP2 and CDK2 were positively correlated in gastric cancer tissues." (PMID 29744291, 2018).